MAOB (monoamine oxidase B)
Diseases named in the same sentence as MAOB in open-access papers (continued):
Sharing a sentence is not in itself a finding about the gene and the disease.
glioma (20 papers, 2016 to 2026). A benign or malignant brain and spinal cord tumor that arises from glial cells (astrocytes, oligodendrocytes, ependymal cells). "MAOB is known to be highly expressed in glioma and was reported to be linked with an adverse prognosis in colorectal cancer." (PMID 37509535, 2023). "Although upregulation and downregulation of MAOB were respectively observed in gliomas and betel nut-associated oral cancer, the role and biologic significance of MAOB in pathogenesis were rarely independently mentioned in those studies." (PMID 32316576, 2020). "MAOB is linked to increased ROS production, which may promote tumor growth in certain instances, and it has paradoxically been associated with better survival outcomes in breast cancer and has also been investigated as a therapeutic target in colon cancer, glioma, and other forms of cancer." (PMID 41009689, 2025). "The same tumor microarray and methodologies were employed to quantify antigen levels as described in our earlier investigation showing high expression of MAOB and transcription factors in human gliomas." (PMID 39456605, 2024). "MP-MUS, which is a prodrug activated by MAOB, reduces the proliferation of glioma cells, and Danshensu, which is an MAOB inhibitor, increases the radiosensitivity of non-small cell lung cancer." (PMID 37509535, 2023). "We have demonstrated that PAM-OBG is able to generate O6BG inside glioma, via MAOB, and that this O6BG then reacts with MGMT inactivating it." (PMID 29844863, 2018). "MAOB generates hydrogen peroxide, and we found high basal rates of reactive oxygen species generation, mostly hydrogen peroxide, in glioma cells as compared to NHA." (PMID 26689994, 2016). "In conclusion, we confirmed that MAOB is highly expressed in glioma and found that the highest grade tumors have the highest expression levels of MAOB." (PMID 26689994, 2016). "The difference between the 4-FBA stimulated and selegiline inhibited rates indicate that the glioma have between 2.3 and 3.7 times more functional MAOB than do NHA." (PMID 26689994, 2016). "Three slides, bearing 20 GBM, 7 lower grade glioma and control human temporal brain tissue, were simultaneously prepared for MAOB, HiF-1α, GFAP immunohistochemical labeling/staining and were imaged in a single session, using identical microscope settings." (PMID 26689994, 2016). "Gliomas have elevated monoamine oxidase B (MAOB), SP1, and HIF-1α levels." (PMID 36077352, 2022). "Conversely, upregulation of MAOB was found in human gliomas and colorectal cancer." (PMID 34209963, 2021). "Monoamine oxidase B (MAOB) levels are correlated with the glioma tumor grade." (PMID 33192553, 2020). "The aim of this paper is to evaluate the biological effects of two potent and selective Monoamine Oxidase B (MAO-B) inhibitors, Cmp3 and Cmp5, in C6 glioma cells and in CTX/TNA2 astrocytes in terms of cell proliferation, apoptosis occurrence, inflammatory events and cell migration." (PMID 31130597, 2019). "Data from the TCGC database indicates that all major glioma sub-types have a similar MAOB mRNA distribution, with the minimum showing > 2.5-fold the level of normal brain tissue, the average ≈ 8-fold greater, and maximal > 30-fold higher (166 GBM, 283 LGG-WT, and 233 LGG-IDH mut)." (PMID 29844863, 2018). "MAOB levels are higher in low-grade glioma and in GBM than in the body’s other tissues." (PMID 29844863, 2018). "This inversion of function, with Sp3 repressing MAOB transcription in GBM and activating it in the astrocytic glioma, may be linked to SUMOylation changes in these glioma, and such a change appears to be linked to tumor grade." (PMID 26689994, 2016). "However, in these glioma MAOB flux was much more tightly constrained by MAOB substrate availability, and on addition of 4-FBA these cells generate between 4 and 6 fold more peroxide than do NHA." (PMID 26689994, 2016). "Here we investigated the level of MAOB in gliomas and confirmed its high expression." (PMID 26689994, 2016).
glioma (continued). "The degree of MAOB upregulation in glioma cells may be a key to future chemotherapeutics." (PMID 26689994, 2016). "We established and validated a robust four-gene signature (MAOB, IGFBP2, SERPINA1 and LGR6) that serve as an independent prognostic biomarker for grade II/III gliomas." (PMID 40821817, 2025). "By identifying differentially expressed genes (DEGs) between subtypes, we constructed a four-gene prognostic signature (MAOB, IGFBP2, SERPINA1, and LGR6) and validated its robustness using the Chinese Glioma Genome Atlas (CGGA) expression dataset." (PMID 40821817, 2025). "Six genes of these essential TrMGs, including MAOB, HSD17B10, KYNU, AOX1, and OGDH, were determined as hazardous factors for glioma patients, and other two genes (CYP2E1 and ALDH2) were identified as protective factors." (PMID 36386216, 2022). "We have designed and tested both in vitro and in vivo, a monoamine oxidase B (MAOB) specific prodrug, PAM-OBG, that is converted by glioma MAOB into the MGMT inhibitor O6-benzylguanine (O6BG) and the DNA crosslinking agent acrolein." (PMID 29844863, 2018). "Expression of MAOB and HiF-1α is highly correlated, with a correlation coefficient (R2) of 0.33 (p = 0.0072) for GBM alone and 0.36 (p = 0.0045) in all the glioma." (PMID 26689994, 2016). "We also compared the cross-correlation of MAOB, HiF-1α and GFAP levels among all the gliomas." (PMID 26689994, 2016). "Thus PAM-OBG can ablate MGMT activity and create acrolein-DNA adducts in glioma cells, but not in tissues with low levels of MAOB." (PMID 29844863, 2018). "To validate the protein-level expression patterns of the prognostic genes in clinical specimens, we performed immunohistochemical (IHC) staining of MAOB, IGFBP2, SERPINA1, and LGR6 on paraffin-embedded sections of glioma tissues and adjacent non-tumorous brain tissues." (PMID 40821817, 2025).
schizophrenia (20 papers, 2011 to 2025). A major psychotic disorder characterized by abnormalities in the perception or expression of reality. "In male patients with schizophrenia, the presence of the MAOB rs1799836 A‐allele, presumably linked to elevated MAOB activity, was associated with a greater severity of negative symptoms." (PMID 38520217, 2024). "The single-nucleotide polymorphism (SNP) rs1799836 of MAOB was selected for association analysis in 537 schizophrenia patients and 536 healthy controls, and it was identified as a risk factor in the development of schizophrenia." (PMID 34881779, 2022). "The strongest association (p = 0.0004) was found between MAOB rs5905512, a SNP previously reported to be associated with schizophrenia in men, and MHPG concentrations in men with psychotic disorder." (PMID 25073638, 2014). "In particular, MAOB allelic variations have been associated with bipolar disorder and higher schizophrenia susceptibility; these results, however, have been not been consistently replicated." (PMID 24639636, 2014). "We analyzed uVNTR and rs1137070, polymorphisms from MAOA and rs1799836 of MAOB genes to perform single SNP case-control association study in a sample of 344 schizophrenia patients and 124 control subjects." (PMID 23738213, 2012). "Here, we investigated the association of MAOA and MAOB polymorphisms with schizophrenia in a Han Chinese population." (PMID 21978760, 2011). "Two functional single nucleotide polymorphisms (SNPs), rs6323 of MAOA and rs1799836 of MAOB, were selected for association analysis in 537 unrelated schizophrenia patients and 536 healthy controls." (PMID 21978760, 2011). "Polymorphisms of isoforms MAOA and MAOB have been implicated in the etiology of mental disorders such as schizophrenia." (PMID 21978760, 2011). "Here, we investigated the association of two representative functional polymorphisms, rs6323 of MAOA and rs1799836 of MAOB, with the development of schizophrenia in Han Chinese." (PMID 21978760, 2011). "It is possible that functional variants in the MAOA and MAOB genes could predispose to antipsychotic-induced weight gain in patients with schizophrenia." (PMID 30967134, 2019). "In particular, numerous articles have recently reported that different MAOB variants may predispose to schizophrenia in women or in men." (PMID 24639636, 2014). "Our preliminary findings could suggest that severity of affective flattening may be associated by modifier variants of MAOA and MAOB genes in female Mexican patients with schizophrenia." (PMID 23738213, 2012). "In conclusion, our preliminary findings could indicate that the severity of negative symptoms might be associated by modifier variants of MAOA and MAOB genes in Mexican patients with schizophrenia, in particular, with affective flattening dimension." (PMID 23738213, 2012). "Our results suggest that MAOB is a susceptibility gene for schizophrenia." (PMID 21978760, 2011). "Although both MAOA and MAOB genes have been suggested as genetic factors in the pathogenesis of schizophrenia, our findings only support the association of MAOB polymorphism with susceptibility to schizophrenia in Han Chinese." (PMID 21978760, 2011). "Moreover, one candidate MAOB SNP, previously reported to be associated with schizophrenia in men, was found to be significantly associated with MHPG concentrations in men with psychotic disorder, performing a correction for multiple testing for the number of candidate SNPs selected." (PMID 25073638, 2014). "In addition, other studies highlighted that MAOB variants may moderate several symptomatic aspects of schizophrenia, including flat affect or paranoid manifestations." (PMID 24639636, 2014). "Several studies suggest that MAOB gene may be implicated in the susceptibility to schizophrenia." (PMID 23738213, 2012).
schizophrenia (continued). "Because increased levels of anionic PS lipids have potential effects on schizophrenia and, more specifically, on monoamine oxidase B enzyme activity, the effect of varying the PS concentration was explored." (PMID 35204684, 2022). "In the context of OMM, the increased POPS levels have been linked to monoamine oxidase B (MOA-B) inactivation and schizophrenia decades ago." (PMID 35204684, 2022). "Midbrain monoamine oxidase A (MAOA) mRNA was increased, whereas MAOB and catechol-O-methyl transferase mRNAs were unchanged in schizophrenia." (PMID 28094812, 2017). "The role of MAO genes in the susceptibility to schizophrenia requires further research; therefore, we analyzed MAOA and MAOB gene polymorphisms to perform single SNP association study in Mexican patients with schizophrenia." (PMID 23738213, 2012). "The distribution of MAOA and MAOB genotypes for schizophrenia and control groups were in Hardy-Weinberg equilibrium (P > 0.05)." (PMID 23738213, 2012). "Study results of 302 Caucasian male and female schizophrenia patients aged 18–62 suggests that some catechol-O-methyltransferase (COMT) and monoamine oxidase B (MAO-B) genetic variants are associated with a sex-specific increase in the severity of negative symptoms." (PMID 34575706, 2021). "A direct implication of MAOB in schizophrenia is supported by several studies and may be reflective of the greater contribution of this enzyme to the metabolism of DA in humans." (PMID 24639636, 2014). "MAOA mRNA was significantly increased by 45% in the substantia nigra in schizophrenia cases compared with controls (F=6.34, df=56, P=0.015), but no diagnostic changes were found in the levels of MAOB mRNA (F=0.81, df=53, P=0.372) or COMT mRNA (U=462, z=0.89, P=0.371)." (PMID 28094812, 2017). "Therefore, it could be possible that genetic variation of MAOB suggests a gender subtype of schizophrenia." (PMID 23738213, 2012). "Interestingly, it has been published that selegiline, a selective monoamine oxidase B inhibitor in combination with antipsychotics could be helpful for treating negative symptoms in schizophrenia." (PMID 23738213, 2012).
Cognitive impairment (19 papers, 2012 to 2026). Abnormal cognition is characterized by deficits in thinking, reasoning, or remembering. "MAOB rs1799836 was associated with the progression of nonmotor symptoms, especially cognitive impairment, and the composite progression of motor and nonmotor symptoms within our Chinese PD cohort." (PMID 36164437, 2022).
mental disorder (15 papers, 2011 to 2025). A disease that has its basis in the disruption of mental process. "We selected these genes because they are included in the list of 115 genes from the GO term: mitochondrion and have been implicated in psychiatric disorders: monoamine oxidase B, NADH dehydrogenase (ubiquinone) flavoprotein, mitochondrial uncoupling protein 5, and tubulin." (PMID 23152871, 2012). "MAOA and MAOB specifically oxidize and inactivate monoamine transmitters, and MAOA gene polymorphisms were associated with susceptibility to METH-induced mental disorders." (PMID 35422687, 2022). "Given the elevated MAOB expression observed in psychiatric disorders and its potential to drive GABA dysregulation, we hypothesize that aberrant astrocytic GABA disrupts inhibitory balance and impairs fear extinction in PTSD." (PMID 40717119, 2025). "Growing evidence indicates that gender-specific effects of MAOA and MAOB exist in various psychiatric diseases, and haplotype analyses support this gender-specific hypothesis." (PMID 21978760, 2011). "Additionally, as emerging reports indicate that MAOA and MAOB may have gender-specific roles in the development of several psychiatric disorders, we have included differences in gender in our statistical analysis." (PMID 21978760, 2011). "Furthermore, three active ingredients, ATR3, ATR15, and ATR102, were shown to interact with MAOA, MAOB, and NOS3, which are related to inflammation and play a role in the pathogenesis and symptoms of mental disorders." (PMID 32802132, 2020).
glioblastoma (13 papers, 2016 to 2026). The most malignant astrocytic tumor (WHO grade IV). "miR‐522 has also been reported to be able to boost colorectal tumorigenesis via targeting BLM, accelerate the progression of endometrial carcinoma by inhibiting MAOB, as well as promote glioblastoma cell proliferation by suppressing PHLPP1." (PMID 33369228, 2021). "Consistent with our results, it has been found that decreasing the mRNA expression level of MAOB can extend the survival time of glioblastoma." (PMID 34819038, 2021). "In glioblastoma, high expression and activity of MAOB has led to the exploration of an MAOB-activated pro-drug and selective MAOB inhibitors as potential treatments." (PMID 33167358, 2020). "Levels of MAOB are correlated by the levels of transcription factor Sp3 in the majority of GBM examined, but this control of MAOB expression by Sp3 in low grade astrocytic gliomas is significantly different from control in the in the majority of glioblastomas." (PMID 26689994, 2016). "By targeting BLM, DENND2D, PHLPP1 or MAOB, miR‐522 could boost tumorigenesis of colorectal cancer, non‐small‐cell lung cancer, glioblastoma and endometrial carcinoma, respectively." (PMID 33369228, 2021).
alcoholism (11 papers, 1995 to 2024). "Independently from ASPD the MAOB haplotype associated significantly with alcoholism (P = 0.006), and antisocial alcoholism (P = 0.03)." (PMID 30542299, 2018). "The fact that several studies have registered different MAOB activity levels in alcoholic and healthy subjects has meant that MAOB levels are considered by some as a genetic marker for alcoholism, although the results are contradictory and highly discussed." (PMID 34679329, 2021). "Low MAOB activity has not only been related to type-II alcoholism, but is also present in alcohol addiction more generally, regardless of age of onset and the presence of antisocial behaviour." (PMID 34679329, 2021). "However, we could not confirm the significant association of MAOB rs1799836 with complex psychiatric and behavioral outcomes in children and adolescents, such as CD (present study), ADHD or autism, alcohol dependence or PTSD in adults." (PMID 33203099, 2020).
Obesity (10 papers, 2019 to 2026). Accumulation of substantial excess body fat. "Low activity genotypes at both the MAOA and MAOB loci – showed a relative risk for obesity of 5.01." (PMID 30967134, 2019).
serotonin syndrome (10 papers, 2020 to 2025). Serotoninergic syndrome is characterized by an excess of serotonin in the central nervous system, associated with the use of various agents, including selective serotonin reuptake inhibitors (SSRIs). "In humans, co-administration of an SSRI (selective serotonin reuptake inhibitors, ex: fluoxetine) and an MAO-B (monoamine oxidase B inhibitor, ex: selegiline) have been reported, though rarely, to be associated with cases of serotonin syndrome." (PMID 41234399, 2025). "The combination of an SSRI with an irreversible monoamine oxidase-B (MAO-B) inhibitor like selegiline is not recommended because of the risk of developing serotonergic syndrome." (PMID 39120709, 2024).
colorectal cancer (9 papers, 2020 to 2026). A primary or metastatic malignant neoplasm that affects the colon or rectum. "In colorectal cancer, MAOB overexpression correlates with advanced staging, recurrence, and poor prognosis." (PMID 40821817, 2025). "In addition, MAOB can be used as a novel biomarker to predict the prognosis of colorectal carcinoma and can affect the progression of esophageal cancer." (PMID 34819038, 2021). "Compared to MAOA, fewer studies have addressed the role of MAOB in cancer except for colorectal carcinoma (CRC), gliomas, PCa, and head and neck cancers, in which cases diverse roles were displayed." (PMID 41338163, 2025).